RNU6-1083P (RNA, U6 small nuclear 1083, pseudogene)
Gene: Small nuclear RNA gene on chromosome 12 (57,806,154 to 57,806,260, reverse strand). Ensembl gene ENSG00000206749.
Homologues: Orthologues: chimpanzee U6 (99% identical), guinea pig U6 (87% identical). Paralogues in human: RNU6-1310P (93% identical), RNU6-797P (90% identical), RNU6-11P (89% identical), RNU6-1316P (89% identical), RNU6-35P (89% identical), RNU6-37P (89% identical), RNU6-726P (89% identical), RNU6-73P (89% identical), RNU6-968P (89% identical), RNU6-1145P (88% identical), RNU6-1181P (88% identical), RNU6-12P (88% identical), and 1287 more.